MUC1 (mucin 1, cell surface associated)
Diseases named in the same sentence as MUC1 in open-access papers (continued):
Sharing a sentence is not in itself a finding about the gene and the disease.
renal cell carcinoma (17 papers, 1999 to 2024). "MUC1 is overexpressed in renal cell carcinoma with correlation to prognosis and has been implicated in the hypoxic pathway, the main renal carcinogenetic pathway." (PMID 24504508, 2014). "Overexpression of mucin 1 (MUC1) can promote cancer cell proliferation by regulating cell metabolism, and tumor-related MUC1 exhibiting loss of apical localization and aberrant glycosylation in kidney cancer, especially in renal cell carcinoma (RCC)." (PMID 39484162, 2024). "The aim of this review is to explore the role of MUC1 and the meaning of its overexpression in epithelial tumors and in particular in renal cell carcinoma (RCC)." (PMID 38540735, 2024). "It has been proved by experiments that the expression level of gene MUC1 in renal cell carcinoma cell lines correlated to resistance to Sunitinib." (PMID 32849855, 2020). "For Renal Cell Carcinoma (RCC), thirty-seven patients with progressive, MUC1-positive tumors received TG4010 108 pfu/injection weekly for 6 weeks, then every 3 weeks until progression, when TG4010 was continued in combination with interferon-α2a and interleukin-2." (PMID 24212974, 2011). "Mucins such as MUC17 and MUC1 have been reported in relevant studies in renal cell carcinoma, although MUC1 was not identified as a survival-specific gene in our study." (PMID 38893126, 2024). "Differences in MUC1 expression can also be used to distinguish between type I and type II papillary renal cell carcinoma (PRCC) and as a marker for distinguishing multilocular cystic renal cell carcinoma (MCRCC) and renal cell carcinoma cystic change (RCC-CD)." (PMID 39491020, 2024).
adenoma (16 papers, 2010 to 2025). A neoplasm arising from the epithelium. "This trial is using multiple antigens that are expressed in precancer and cancer cells (CEA/MUC1/Brachyury) along with IL-15 Superagonist N-803 to measure the incidence of adenomas and elicited immune responses." (PMID 40437549, 2025). "Individuals with advanced adenoma received MUC1 peptide vaccine within 1 year after adenoma removal." (PMID 38890350, 2024). "From 2015-2020, we conducted the second study, a randomized, double-blind placebo-controlled multi-center efficacy trial of the same MUC1 vaccine in the setting of newly diagnosed advanced adenomas in 110 individuals (NCT-02134925)." (PMID 39450169, 2024). "A phase 2 trial of another MUC1 vaccine is currently underway to evaluate its ability to decrease recurrence rates in patients with a history of advanced adenoma (those with high-grade dysplasia, villous/tubulovillous features, or tumors larger than 1 cm)." (PMID 36900282, 2023). "A phase I/II study in patients with a history of colorectal adenoma demonstrated MUC1 immunogenicity and a phase II trial investigating the ability of MUC1 vaccine to prevent adenoma recurrence is currently ongoing." (PMID 32283684, 2020). "H&E-stained sections showed that MUC1.Tg mice developed adenomas with high-grade dysplasia and higher inflammation score compared to WT mice." (PMID 29285251, 2017). "Tissue samples of polyps or adenomas showed variable intensity of hypoglycosylated MUC1, phospho-p65 and EzH2 expression, from very low to moderately high." (PMID 29285251, 2017). "A more recent study showed 100% Muc1 expression in colonic adenocarcinomas and 76% expression in adenomas, relative to 29% Muc1 expression by mucosa within 2 cm of the cancer margin, and 0% expression by normal mucosa > 2 cm from the cancer margin." (PMID 23905030, 2011). "Higher levels of MUC1 expression was also observed among traditional adenomas especially tubulovillous and villous adenomas." (PMID 20929551, 2010). "The expression of MUC1 was significantly higher in traditional adenomas than serrated adenomas/hyperplastic polyps (23.5% vs. 7.8%, P = 0.005)." (PMID 20929551, 2010). "Given the cancer immunoprevention potential of the MUC1 peptide vaccine response, characterized by a reduction of adenoma recurrence, the differentially expressed genes and regulated pathways we identified hold promise as therapeutic targets for vaccine non-responders." (PMID 39450169, 2024). "We then paired the percent MDSC with anti-MUC1 IgG level for each patient with adenoma." (PMID 31275327, 2019). "In the Colon Cohort, the adenoma group had the highest average level of anti-MUC1 IgG." (PMID 31275327, 2019). "However, sometimes they can show focal staining with MUC5A (a foveolar marker, positive in gastric foveolar-type adenomas) and MUC1 (a pancreatobiliary marker, positive in biliary-type adenomas)." (PMID 30662921, 2018). "In contrast, increased MUC1 positivity has been reported in conventional adenomas." (PMID 27705923, 2017). "However, higher levels of MUC1 in TA along with reports of its even higher expression in CRC, and association with invasion risk argue for the potential applicability of MUC1 expression as a predictor of malignant transformation in the adenoma-carcinoma sequence." (PMID 27705923, 2017). "MUC1 and MUC6 were absent in all hyperplastic polyps and their expression was higher in serrated and traditional adenomas." (PMID 20929551, 2010).
ovarian tumor (16 papers, 2009 to 2025). "The differentiated subtype was associated with high expression of ovarian tumor markers (MUC1 and MUC16) and the secretory fallopian tube marker SLPI, suggesting a more mature stage of development." (PMID 40953111, 2025). "In non-ovarian tumor cell types, the binding of Gal-3 to cancer associated TF/MUC1 induces redistribution of MUC1 on the cell surface, increasing cancer cell homotypic aggregation and the formation of tumor micro-emboli." (PMID 32486344, 2020). "Some of our ovarian tumor models are derived from the OSE of MUC1 transgenic mice and express human MUC1." (PMID 40642792, 2025). "A recent study using a triple transgenic MUC1/Kras/Pten mouse model also showed that MUC1 positive ovarian tumors have a greater capacity for metastatic spread." (PMID 26492273, 2015). "The tumors have well defined (endometrioid) histology, and, as with ovarian tumors, overexpress MUC1 and trigger detectable levels of spontaneous MUC1-specific humoral responses, closely mirroring the immunogenicity seen in the respective human diseases." (PMID 25078979, 2014). "We have previously shown that triple transgenic MUC1KrasPten mice, injected with AdCre under the ovarian bursa, develop human MUC1-expressing ovarian tumors, closely mirroring the human disease." (PMID 25078979, 2014). "Different studies on the expression of mucins in ovarian tumors have shown overexpression of MUC1, MUC2, MUC3, MUC4, MUC5AC and MUC16 or CA125." (PMID 20034397, 2009). "Our recent and some previous studies showed the overexpression of MUC4 in a majority of early stage ovarian tumors and a combined panel of MUC1, MUC4 and MUC16 dramatically increased the sensitivity of MUC16 staining test." (PMID 20034397, 2009). "The overexpression of MUC1 in various types and stages of ovarian tumor samples is reported in several studies." (PMID 20034397, 2009). "However, in breast and ovarian tumors, MUC1 was observed to be underglycosylated and assumed an additional intracellular localization that is associated with poor prognosis." (PMID 26492273, 2015). "MoDCs readily engulfed HOCl-oxidized SKOV3 ovarian tumor cells, and when matured with either monophosphoryl lipid A or anti-CD40 activating antibody, they could stimulate strong T cell responses directed against specific ovarian tumor-associated antigens such as HER-2/neu and MUC1." (PMID 22082029, 2011). "The proliferative subtype was identified by the overexpression of transcription factors HMGA2 and SOX11, proliferation marker genes such as MCM2 and PCNA, and underexpression of MUC1 and MUC16, which are known ovarian tumor marker genes." (PMID 25611546, 2015). "Various studies have shown the overexpression of MUC1, MUC2, MUC3, MUC4, MUC5AC and MUC16 in a variety of ovarian tumors." (PMID 20034397, 2009). "The much higher expression of mucins (MUC1, MUC4, MUC5AC, MUC13 and MUC16) in ovarian tumors compared to the surrounding normal tissues can be exploited for the purpose of radioimmunodiagnosis (RID) and radioimmunotherapy (RIT)." (PMID 20034397, 2009). "Several ovarian biomarkers, such as Kallikreins, osteopontin, leptin, HE-4, LPA, MUC1 and SLPI, have been identified in the past several years through various approaches, including gene expression profiling and proteomics analysis of ovarian tumors." (PMID 19619303, 2009). "MUC1 and MUC4 are also known to be overexpressed in ovarian tumors." (PMID 20034397, 2009). "Interestingly, while traditional organoids derived from the same MUC1 and CD276 positive ovarian tumor tissue showed little or no activation, PSO demonstrated a significant level of activation." (PMID 38162496, 2023).
pancreatic adenocarcinoma (16 papers, 2004 to 2025). "MUC1 is a tumor-associated antigen that is over-expressed in pancreatic adenocarcinomas." (PMID 19534821, 2009). "MUC1 is a tumor-associated antigen that is over-expressed in pancreatic adenocarcinoma." (PMID 19534821, 2009). "This review explores the mechanisms by which MUC1 contributes to cancer onset and progression, with a focus on its potential role as a biomarker and novel therapeutic target for pancreatic adenocarcinoma treatment." (PMID 40001578, 2025). "An important correlation exists between pancreatic adenocarcinoma and MUC1, a glycoprotein of the mucin family." (PMID 40001578, 2025). "Under pathological conditions, such as colon adenocarcinoma and pancreas adenocarcinoma or stomach adenocarcinoma, MUC1 would change its expression fashion and rate." (PMID 27190429, 2016). "For example, injection of syngeneic pancreatic adenocarcinoma cells in the pancreas resulted in enhanced tumor growth compared to subcutaneous sites and differential expression of the tumor antigen Muc1." (PMID 25687736, 2015). "In experimental pancreatic adenocarcinoma, the combined treatment with mucin-1- (MUC1-)based vaccine and celecoxib, a COX-2 inhibitor, elicited vigorous antitumor responses." (PMID 22567028, 2012). "The presence of MUC1 in these transgenic mice enhanced PanIN progression and development of pancreatic adenocarcinoma via an immunosuppressive effect due to a higher level of cyclooxygenase-2 or indoleamine 2,3-dioxygenase." (PMID 24281201, 2010). "In this paper, we showed that a MUC1 DNA vaccination strategy succeeded in suppressing pancreatic adenocarcinoma in C57BL/6 mice." (PMID 19534821, 2009). "The main difference between adenocarcinoma of the pancreas and IPMT is an increased expression of MUC2 associated with a decreased expression of MUC1 in IPMT vs adenocarcinoma." (PMID 15494719, 2004). "Therefore, they scientifically proved that MUC1 was a regulator of Met signal transduction in pancreatic adenocarcinoma cells." (PMID 35709153, 2022). "Notably, down-regulation of MUC1 expression using RNA interference decreases the metastatic potential of pancreatic adenocarcinoma in vivo." (PMID 24281201, 2010). "Indeed, sTn is detected at the surface of MUC1 overexpressed by pancreatic adenocarcinoma cells." (PMID 15494719, 2004). "Notably, BRCA (Breast invasive carcinoma) and PAAD (Pancreatic adenocarcinoma) express high level of MUC1, yet LUSC (Lung squamous cell carcinoma) and SKCM (Skin Cutaneous Melanoma) barely express MUC1." (PMID 35970845, 2022). "Mab-PAM4 has been recently proposed as a promising anti-MUC1 antibody which reacts with 85% of pancreatic adenocarcinomas while showing no reactivity against normal pancreas or other tissues." (PMID 24281201, 2010).
endometriosis (15 papers, 2011 to 2026). The growth of functional endometrial tissue in anatomic sites outside the uterine body. "Repression of lncRNA MALAT1 enhances the susceptibility of endometriosis to erastin-induced ferroptosis by regulating the miR-145-5p/MUC1 pathway." (PMID 40303288, 2025). "This study aims to assess endometrial receptivity in endometriosis by evaluating differences in the frequencies of MUC-1 and COX-2 gene polymorphisms associated with endometrial receptivity." (PMID 38313170, 2023). "Therelationship between the single nucleotide polymorphisms in the MUC1 and MUC4genes and endometriosis risk was analyzed in this study." (PMID 37153512, 2023). "Because of the functions involved in the acquisition of adhesion ligands or receptors and the loss of antiadhesion, proteins such as MUC4 and MUC1, the two major mucins present in endometrial epithelium, thus become suspect in endometriosis development." (PMID 21349170, 2011). "Several studies demonstrated the altered expression of MUC1 in women undergoing RIF, recurrent pregnancy loss (RPL), PCOS, and endometriosis." (PMID 38474081, 2024). "For instance, the lncRNA ROR/miR-145-5p axis promotes osteoblast proliferation in osteoporosis, and silencing of lncRNA MALAT1 enhances erastin-induced ferroptosis in endometriosis via the miR-145-5p/MUC1 signaling pathway." (PMID 39308922, 2024). "This study investigated the relationship between MUC-1 and COX-2 polymorphisms and endometrial receptivity in endometriosis patients." (PMID 38313170, 2023). "It has also been reported that lncRNA metastasis‐associated lung adenocarcinoma transcript 1 (MALAT1) acts as a competitive endogenous RNA of miR‐145‐5p to regulate the expression of ferroptosis inhibitor mucin 1 (MUC1) and promote erastin‐induced ferroptosis in endometriosis." (PMID 40821694, 2025). "Human MUC1 TG mice have since been crossed with conditional-endometriosis transgenic mice, showing the presence of regulatory Foxp3+ T cells and antibodies against MUC1 during endometriosis, with potential implications for cancer progression." (PMID 23509794, 2013). "MUC1 IgG ab levels were significantly higher in patients with benign ovarian tumors and in patients with ovarian or endometrial cancer than in healthy controls or patients with endometriosis." (PMID 24212946, 2011). "In conclusion, combining MUC-1 and COX-2 (AAGC) genotypes results in endometrial receptivity defects in endometriosis." (PMID 38313170, 2023). "The combination of MUC-1 and COX-2 genotypes (AAGC) leads to defects in endometrial receptivity in endometriosis." (PMID 38313170, 2023). "There were several genes strongly expressed in endometriosis tissue: EPCAM, KRT18, WT1, MUC16, MUC1, and ESR1, if compared to the endometrial cells from healthy controls." (PMID 31717910, 2019). "Both ovulatory and anovulatory PCOS and fertile samples showed increase levels of MUC1 after treatment with progesterone, while cells from endometriosis samples did not respond to hormone stimulation." (PMID 38474081, 2024). "Indeed, patients with ovulatory PCOS showed levels of MUC1 higher than fertile and anovulatory PCOS patients, whereas endometriosis women showed a significant reduced expression of MUC1 compared to fertile samples." (PMID 38474081, 2024).
leukemia (15 papers, 2006 to 2025). A malignant (clonal) hematologic disorder, involving hematopoietic stem cells and characterized by the presence of primitive or atypical myeloid or lymphoid cells in the bone marrow and the blood. "mRNA electroporation is a non-viral gene transfer method; only one study implemented an (adeno)viral transduction approach for gene transfer of the leukemia-associated antigens survivin and MUC1." (PMID 31035598, 2019). "Peptide vaccines mainly target leukemia-associated antigens including nephroblastoma 1 (WT1), protease 3 (PR3), hyaluronic acid-mediated motor receptor (RHAMM), and mucin 1 (MUC1)." (PMID 40129984, 2025). "This CAR-T cell inhibits the growth of MUC1-Tn-positive cancer cells in the mouse model of leukemia and PAAD." (PMID 37894512, 2023). "Furthermore, as evidenced for CAR19 treatment of leukemia and as was also shown in an in vivo model of PSCA and MUC1-positive tumors, heterogeneous target antigen expression may lead to tumor escape variants when a single CAR T therapy is used." (PMID 28515942, 2017).
mucinous carcinoma (15 papers, 2005 to 2025). "Increased expression of MUC1 in BilIN (MUC2−/CK7+/CK20− pattern) and IPNB (MUC2+/CK7+/CK20+) is associated with tubular adenocarcinoma, while colloid carcinoma in IPNB is characterized by MUC1-negativity and less advanced pathologic stages." (PMID 30875782, 2019). "Mucinous adenocarcinoma differed from other histologic subtypes regarding MUC1 and MUC5AC expression." (PMID 36367122, 2023). "In case 4, MUC1 was expressed in the cytoplasm, which was enhanced compared with mucinous carcinoma." (PMID 37337182, 2023). "In our study, mucinous adenocarcinoma differed from other histologic subtypes regarding MUC1 and MUC5AC expression." (PMID 36367122, 2023). "Mucinous adenocarcinoma showed less MUC1 expression with lower IRS scores and higher MUC5AC expression." (PMID 36367122, 2023). "Similar to our results, mucinous adenocarcinomas showed apical MUC1 expression in less than 50% of tumors and was more commonly expressed in lepidic predominant adenocarcinomas compared with invasive mucinous adenocarcinomas in the literature." (PMID 36367122, 2023). "The mucinous adenocarcinoma characterized genes, such as MUC1 and MUC2, were significantly enriched in cancer cells from CRC2." (PMID 36038820, 2022). "Expression of MUC1 was significantly associated with T and N classification, AJCC/UICC stage, and tumor differentiation and inversely correlated with mucinous adenocarcinoma histological type." (PMID 27298226, 2016). "They supposed two progression pathways of IPNB to tubular adenocarcinoma and mucinous carcinoma, featuring the phenotypes of MUC1+/MUC2+ and MUC1−/MUC2+, respectively, which are analogous to that of IPMN of the pancreas." (PMID 24949206, 2014). "Majority of tissue spots from mucinous adenocarcinoma were mildly positive for MUC1 (mean H-score, 0.62±0.14)." (PMID 24671186, 2014). "Choi and his colleagues found mucinous adenocarcinoma always showed MUC1- and MUC2+ in a study of 133 MA cases, which was consistent with the result of our study." (PMID 23937908, 2013). "When analyzing different histological GC groups, we found the phenotype of PGC-/MUC1-/MUC2+ all distributed in the group of mucinous adenocarcinoma or signet ring cell carcinoma (MA or SRCC, 100%, 6/6)." (PMID 23937908, 2013). "In contrast, overexpression of MUC1, which is present on the apical surface of normal secretary epithelium, has been demonstrated in the surface membrane of mucinous carcinoma cells, as well as in the cytoplasm of IDCs and intracytoplasmic vacuoles of ILCs." (PMID 20550696, 2010). "MUC1 IRS scores were moderate to high in acinar, lepidic, papillary, micropapillary, and solid patterns of non-mucinous adenocarcinomas." (PMID 36367122, 2023). "The other reason lies within the surface glycoproteins present in colloid carcinoma: MUC1 is present in PDAC on the luminal aspect or throughout the cells, whereas CC expresses MUC1 on the basal surface." (PMID 37627978, 2023). "Colloid carcinomas are generally positive for CK7 and CDX2 and weak or negative for TTF1, napsin A and EMA (MUC1)." (PMID 41473421, 2025). "In a similar manner, in the HMucBOT-2 tumor, mucinous carcinoma lesions expressed all of these markers, with undifferentiated lesions exhibiting PAX8 expression but not CK7 or MUC1 expression." (PMID 40427213, 2025). "Among these special histological types, mucinous carcinoma and IMPC frequently had Ap MUC1 staining patterns (35% and 71%, respectively), while no invasive lobular carcinomas had Ap patterns." (PMID 37002293, 2023).